CDKN2A (cyclin dependent kinase inhibitor 2A)
Diseases named in the same sentence as CDKN2A in open-access papers (continued):
Sharing a sentence is not in itself a finding about the gene and the disease.
tumor (continued). "Univariate analysis of gene expression data on tumor aggressiveness (NMIBC versus MIBC) using logistic regression showed genes, including CDKN2A, CTSV, FOXM1, and KRT23, were predictive of tumor aggressiveness." (PMID 34885040, 2021). "For example, well-known tumor suppressors or tumor-related genes (CDH1, CDKN2A, DAPK, etc.)are silenced by promoter methylation in CC." (PMID 34745985, 2021). "Among overlapping downregulated genes in BA patients versus WA patients in both tumor and TAS are tumor suppressors p16 (CDKN2A), filamin A (FLNA) and ladinin 1 (LAD1)." (PMID 34316327, 2021). "Tumor-suppressor genes BAX, CDKN2A, and MSH5 were negatively correlated with LEPROT in multiple cancer types, and most tumor-suppressor genes were suggested to be positively correlated with LEPROT in a gene-consistent way across cancer types." (PMID 34804118, 2021). "The mRNA expression of the CDKN2A and PLAU genes in OSCC tumor tissues was higher than that in normal tissues." (PMID 33968767, 2021). "The results of univariate analysis demonstrate that CDKN2A, CTSV, FOXM1 and KRT23 were predictive of tumor aggressiveness (MIBC) and the odds of having MIBC was increased by 3% per unit increase of CDKN2Aa (p = 0.01)." (PMID 34885040, 2021). "At the same time, macrophage infiltration and methylation of the cyclin-dependent kinase inhibitor 2A, CDKN2A occurs in the tumor microenvironment." (PMID 34203649, 2021). "We stained a subset of 28 tumours with antibodies against BAP1 and MTAP (as a potential surrogate marker for CDKN2A deletion) along with PD-L1, VISTA, Ki-67 and an antibody for mitotic count." (PMID 34580349, 2021).
tumor (continued). "The gene deletion of CDKN2A and CDKN2B in tumor cells resulted in high activities of CDK4/CDK6, and made cells transit from G1 phase to S phase leading to rapid cell proliferation." (PMID 32860670, 2020). "It appears that at least in NF1-associated MPNSTs, progression from benign to malignant status frequently proceeds through sequential inactivation of three tumor suppressors: NF1, CDKN2A/B, and SUZ12 and/or EED (PRC2 complex)." (PMID 32642732, 2020). "STAT3 also mediates oncogenesis by recruiting DNA methyltransferase 1 (DNMT1) to gene promoters to silence tumours suppressor genes, such as PTPN6, IL-2Rγ, CDKN2A, DLEC1, and STAT1 by CpG methylation in malignant T lymphocytes and breast cancer cells." (PMID 33086505, 2020). "A wide range of tumor-suppressor genes, such as CDH1, CDKN2A (p16), and MLH1, are silenced by aberrant methylation of their promoter CpG islands (CGIs)." (PMID 32958049, 2020). "Meanwhile, frequently deleted genomic regions included tumour suppressor genes such as PARK7 (1p36.23), CDKN2A (9p21.3), and PTEN (10q23.3)." (PMID 32762688, 2020). "To test the role of Cdkn2a for tumour immune control in vivo, we injected the tumour cell lines into syngeneic mice and again started treatment with ICB once tumours reached a diameter >3 mm." (PMID 32165639, 2020). "We observed a decreasing expression level of HSPB8 and PRKN and an increasing expression level of EGFR, CDKN2A, FADD, and ITGA3 in tumor samples." (PMID 33456497, 2020). "In this study, the methylation status of five selected gene promoters (CDKN2A, hMLH1, MGMT, CSF2, and DIS3L2) confirmed the presence of DNA methylation in tumor tissues and matched normal tissues." (PMID 31924802, 2020). "CDKN2A/B status remained an independent prognostic factor in Cox regression when adjusting for WHO grade, DNA methylation-based classification, tumor location, age and sex (online resource)." (PMID 32642869, 2020). "Patients’ and PDX tumours both carried CCND1 amplification and a homozygous deletion of CDKN2A was identified in PDX." (PMID 32792481, 2020). "In fact, a previous study reported that UHRF1 forms a complex with HDAC1 and binds to methylated promoters of tumor suppressor genes such as CDKN2A, suggesting that UHRF1 mediates the tumor suppressor repression in cooperation with HDAC1." (PMID 31782885, 2020). "Other co-alterations that have a potential impact on tumor biology include KEAP1 (4%) and combined CDKN2A/CDKN2B (4%)." (PMID 32295619, 2020).
tumor (continued). "In ductal but not lobular tumors, significant inverse correlations were observed between the tumor levels of miR-10b and miR-30c and the mRNA levels of cancer-relevant target genes SRSF1, PIEZO1, MAPRE1, CDKN2A, TP-53 and TRA2B, as well as tumor grade." (PMID 30658617, 2019). "Since the transforming capacity of C11orf95-RELA, a characteristic fusion of ST-EPN-RELA tumors, was reported in Cdkn2a-null embryonic NSCs9, we tested the suitability of our electroporation system for ST-EPN tumor modeling using similar conditions." (PMID 31477715, 2019). "DNA methylation of tumor suppressor genes APC, BRCA1, CDKN2A at their promoter regions blocks transcription activity, which is thought to be associated with human PDACs." (PMID 31540286, 2019). "Many tumor suppressor genes, such as BRCA1/2 and CDKN2A/B, are frequently silenced by DNA methylation and inactive chromatin marks." (PMID 31497535, 2019). "ANRIL is involved in the expression regulation of three tumor suppressor genes at the CDKN2A/B locus (p16-CDKN2A, p15-CDKN2B, and p14-ARF), via a cis-acting, polycomb-mediated epigenetic mechanism." (PMID 31694342, 2019). "CDKN2A is an inhibitor of cyclin-dependent kinase 4 (CDK4) and CDK6, and it functions as a tumor suppressor." (PMID 30034186, 2018). "Virus-induced DNA hypermethylation is commonly found on several tumor suppressor genes including RASSF1A, p16 (also known as cyclin dependent kinase inhibitor 2A (CDKN2A)), TP73, p21 (also known as CDKN1A), and retinoblastoma-associated protein (pRb)." (PMID 29438328, 2018). "The CDKN2A locus codes for two different proteins p16(INK4a) and p14(ARF) (known as p19ARF in mouse), both having tumor suppressor activity in gliomas." (PMID 29654229, 2018).
tumor (continued). "Since the expression level of CDKN2A and CDKN2B are critical to tumorigenesis, we believe the CN losses of these two genes contribute to the malignancy of the tumor." (PMID 30567531, 2018). "By integrating genomic and transcriptomic studies of NPC PDX model, we were able to discover copy number of CCND1 and CDKN2A are the potential drug target of CDK inhibitor, palbociclib, to suppress tumor growth." (PMID 30236142, 2018). "Indeed, by correlating gene expression with zygosity status, they found that CDKN2A expression levels were normal or even elevated when associated at heterozygous gene loss, and proposed rather that KLHL9 and MTAP would concurrently and in a context-dependent manner promote tumor aggressiveness." (PMID 30558563, 2018). "Knockdown of members of this Polycomb group complex led to increased expression of the CDKN2A and CDKN2B tumor suppressors in the Chr9p21 locus." (PMID 30460243, 2018). "The discovery of cancer-associated hypermethylation of the gene cyclin-dependent kinase inhibitor 2A (CDKN2A), coding for a CDK inhibitor protein also known as p16, marked one of the earliest demonstrations of a tumor-driving role of DNA hypermethylation." (PMID 29649096, 2018). "Methylation levels ≥ 25% were only obtained for the promoters of APC in 44% (8/18), BRCA1 and CDKN2A in 11% (2/18) and ESR2 in 12% (2/17) of the tumor tissues and in addition for ESR2 in 6% (1/18) of the tumor-distant tissues." (PMID 28403857, 2017). "Tumor of patient 12, belonging to the triple negative subtype, showed the lowest methylation status (methylation status < LOQ) of CDKN2A exon 2 among all tumors investigated." (PMID 28403857, 2017). "Of TCGA KIRC tumours (n=525), 87, 13 and 31% had VHL inactivation, MYC activation and CDKN2A deletion, respectively." (PMID 28593993, 2017). "Genomic profiling revealed that he harbors a heterozygous deletion in the germline of chromosome 9p21.3 encompassing the CDKN2A and CDKN2B tumor suppressor genes." (PMID 28699883, 2017). "In case of BRCA1 (r = 0.994, p < 0.001), exon 2 of CDKN2A (r = 0.651, p = 0.003) and ESR2 (r = 0.580, p = 0.015), methylation levels in tumor-adjacent tissues correlated with those in tumor-distant tissues." (PMID 28403857, 2017). "In the CNV analysis of individual genes, the copy number state of the CDKN2a, MLH1, and FGFR1 genes is identical in the primary tumour and the cell lines." (PMID 28304377, 2017). "We have previously shown that SS18-SSX interacts with its partners at promoters recognized by ATF2, repressing transcription at critical tumor suppressor loci including EGR1 and CDKN2A." (PMID 28056055, 2017). "Our mouse models of pRCC and ccRCC faithfully recapitulate the genomics of human RCC although the incidence of ccRCC tumours that have coincident VHL and CDKN2A inactivation, along with MYC activation is only ∼6%." (PMID 28593993, 2017). "Four of these genes (ARID1A, APC, CDKN2A, and ID3) showed significantly reduced protein expression in the majority of tumor samples, whereas the remaining four genes displayed changes only in a few tumors." (PMID 29109526, 2017). "CDKN2A/p16INK4a aberrations were detected in all tumors/models, except original tumor-3 and CAM model-3 (i.e., PDAC-3 tumor and CAM model)." (PMID 28304379, 2017). "CDKN2A (also known as p16-INK4a, MTS-1, or CDK4I) is the tumor suppressor, which regulates cell cycle progression by inhibiting cyclinD-CDK4 and cyclinD-CDK6 complexes responsible for initiating the G1/S phase transition." (PMID 28452926, 2017).
tumor (continued). "Among these lncRNAs, BANCER (BRAF-activated lncRNA) regulates the migration invasion and proliferation of tumor and the lncRNA VAD was up-regulated on OIS and activates CDKN2A locus, and this promotes senescence." (PMID 28400982, 2017). "ANRIL is thought to regulate the INK4/ARF tumor suppressor locus; therefore, we examined expressions of two CDKN2A transcripts (p16INK4A and p14ARF) and one CDKN2B transcript (p15INK4B)." (PMID 27055116, 2016). "Most allelic deletions were detected, telomeric to the CDKN2A region at D9S916, with 11 out of 52 informative tumours (21%) displaying LOH." (PMID 27682877, 2016). "For example, the hypermethylation of four genes, CDKN2A, cadherin 13 (CDH13), RASSF1, and APC, can be used to predict tumor progression of stage 1 non-small cell lung cancer (NSCLC)." (PMID 27895806, 2016). "In support of this, we observed modulation of other pathways that would predict sensitivity to EZH2 inhibition, including increased CDKN2A, which is both a known target of PRC2/EZH2 as well as a tumor suppressor." (PMID 27391784, 2016). "Most allelic deletions were detected, telomeric to CDKN2A region at D9S916, with 11 out of 52 informative tumours (21 %) displaying LOH." (PMID 27465101, 2016). "Apart from mutations in epigenetic enzymes, mistargeting of epigenetic enzymes, such as the silencing of CDKN2A and MLH1 by aberrant promoter DNA methylation, is considered to drive tumor formation." (PMID 27895806, 2016). "To better understand the genomic profile of CDC tumors, we performed whole exome sequencing and RNASeq analysis of 7 CDC tumors and 4 matched non-tumor kidney tissues, as well as FISH analysis of CDKN2A on 16 CDC tumors." (PMID 27144525, 2016). "In this study we explore the significance of MYCN, HMGA2, CDKN2A and DICER1 in NSCLC tumours by gene expression analysis." (PMID 26858029, 2016). "In the high glucose condition, PRMT5 was shown to emphatically interact with CDK4, releasing it from CDKN2A and leading the CDK4-RB-E2F axis to an active state for tumor growth." (PMID 27708221, 2016). "While the PTEN loss is also reported in COSMIC for COLO829, no copy number changes were identified to impact the BRAF, or CDKN2A, loci for the COLO829 tumor in COSMIC22." (PMID 27094764, 2016). "Gene expression of MYCN, HMGA2, CDKN2A and DICER1 were investigated with RT-qPCR in surgically resected NSCLC tumour tissue from 175 patients." (PMID 26858029, 2016). "CDKN2A (also known as P16-INK4A) was the most common target of HDs (53 out of 2,087 tumours with copy number data)." (PMID 27161491, 2016). "Of the 68 cases with informative markers within the coding region of CDKN2A (D9S974 and D9S942), LOH was observed in 17 tumours (25.7%), with 7 tumours showing LOH at both microsatellites and 10 tumours showing LOH for one of the two markers." (PMID 27682877, 2016). "Tumor biopsies were methylated in 1/5 (20 %), 2/5 (40 %), 4/5 (80 %), and 4/5 (80 %) for the CDH1, CDKN2A, DAPK, and TIMP2 genes, respectively." (PMID 26363785, 2015). "Tumor biopsies were methylated in 1/5 (20 %), 2/5 (40 %), 4/5 (80 %), and 4/5 (80 %) for CDH1, CDKN2A, DAPK, and TIMP2 genes, respectively." (PMID 26363785, 2015).